BRCA1 (BRCA1 DNA repair associated)
Diseases named in the same sentence as BRCA1 in open-access papers (continued):
Sharing a sentence is not in itself a finding about the gene and the disease.
ovarian carcinoma (continued). "Recently, another mutation in the same codon of BRCA1 (p.R1699Q) was described as an intermediate risk factor in the development of breast and ovarian cancer." (PMID 30040829, 2018). "They found BRCA mutations in 26 of 98 ovarian cancer patients (28%), also reporting the Mexican founder mutation BRCA1 ex9-12del in 35% of their patients from central Mexico." (PMID 29997359, 2018). "Germline mutations in the BRCA1 gene are associated with an elevated risk of breast and ovarian cancer." (PMID 30652068, 2018). "The penetrance of breast and ovarian cancer in BRCA1/2 mutation carriers has been well characterized in Caucasian but not in Asian." (PMID 29861850, 2018). "Germline pathogenic variants in the breast cancer type 1 susceptibility gene BRCA1 are associated with a 60% lifetime risk for breast and ovarian cancer." (PMID 29996917, 2018). "Breast cancer type 1 susceptibility protein (Brca1) was originally cloned as a human tumor suppressor, with mutations in the gene associated with an increased risk of developing breast and ovarian cancers." (PMID 29673145, 2018). "Some women with genetic risk of breast and/or ovarian cancer (e.g., BRCA1/2) opt to undergo prophylactic salpingo-oophorectomy (PSO, or surgical removal of the ovaries & fallopian tubes) in order to reduce their risk of cancer." (PMID 30766717, 2018). "Poly(ADP-ribose) polymerase inhibitor olaparib has recently received FDA approval for treatment of ovarian cancer with mutated BRCA1/2 and EMEA approval for maintenance therapy for platinum-sensitive ovarian cancer." (PMID 29459887, 2018). "Familial risk is associated with mutations in BRCA1 and BRCA2 genes, which conferred respectively 59% and 16.5% risk of developing ovarian cancer by the age of 70 in the Epidemiological Study of BRCA1 and BRCA2 mutation carriers (EMBRACE) in the UK." (PMID 30281663, 2018). "The reported prevalence of BRCA1/2 mutations in patients with ovarian cancer varies across different studies and ethnic populations." (PMID 30103829, 2018). "Somatic BRCA1/2 pathogenic variants are found to be present in up to 7% of ovarian cancers in the first line or platinum‐sensitive relapsed clinical setting." (PMID 29215764, 2018). "Of eighty four patients (84/95; 88.4%) with first and/or second-degree family history of breast and/or ovarian cancer; 22 (26.2%) had deleterious/suspected deleterious mutations in either BRCA1 (7; 8.3%) or BRCA2 (15; 17.9%)." (PMID 29409476, 2018). "BRCA1 mutation-carrying women have significantly higher risk of developing breast and ovarian cancers compared to the general population, with an estimated cumulative risk of 65% and 39% by the age of 70, respectively." (PMID 30558184, 2018). "The results of this interesting study showed that cumulative risk of developing ovarian cancer by age 60 and 80 respectively, were 0.60 and 0.83 from BRCA1 and 0.33 and 0.72 for BRCA2 carriers." (PMID 29389895, 2018). "The PARP1 inhibitor, olaparib, has been approved to treat breast and ovarian cancer patients who have germline mutations in BRCA1/2." (PMID 29783721, 2018). "The risk estimates of breast and ovarian cancer in BRCA1/2 mutation carriers have been well characterized for Caucasian women and individuals of Ashkenazi-Jewish background." (PMID 29861850, 2018). "For example, a finding of deleterious mutations in the BRCA1 or BRCA2 genes associates diagnosed women with high frequency of developing breast or ovarian cancer." (PMID 29636096, 2018). "Germ-line mutations in breast cancer susceptibility gene 1 (BRCA1) predominantly predispose women to breast and ovarian cancers." (PMID 30558184, 2018). "The BRCA1 gene was first identified as a strong candidate gene influencing susceptibility to breast and ovarian cancer." (PMID 29492227, 2018).
ovarian carcinoma (continued). "The most common genes predisposing to ovarian cancer are BRCA1/2, which are associated with high-grade serous histology." (PMID 30069056, 2018). "The proportion of patients diagnosed with ovarian cancer and the germline mutation found in the project was 17% with the BRCA1 gene and 2% with the BRCA2 gene." (PMID 30517521, 2018). "The most common reasons for testing were a family history of breast or ovarian cancer or a known BRCA1/2 mutation in the family, which was present in 98 of the 102 patients." (PMID 29433453, 2018). "Worth pointing out, the gene spectrum, including data on the OCCR and the recurrent mutations described, does not visualize a panel or hot spot of mutations to abbreviate the analysis of BRCA1/2 in our ovarian cancer population." (PMID 30103829, 2018). "We analysed BRCA1/2 germline mutations in 562 high-risk cases with breast and/or ovarian cancer from Andalusian families from 2010 to 2015." (PMID 29884136, 2018). "Loss of Xist seemed related with breast cancer-associated gene 1 (BRCA1) mutation in ovarian cancer, but the conclusion remained controversial, which will be discussed in the below in the manuscript." (PMID 29921308, 2018). "The tumor suppressor genes BRCA1/2 are frequently mutated in familial breast and ovarian cancer, and around 10% of women diagnosed with these pathologies carry BRCA1/2 mutations." (PMID 29882812, 2018). "Upper gastrointestinal tract cancers frequently occur in MLH1 mutation carriers, whereas ovarian cancer occurs mainly in younger women, which is contrary to ovarian cancers in BRCA1/2 mutation carriers and in the general population." (PMID 29849630, 2018). "Chromatin immunoprecipitation investigated that BRCA1 associated with Xist and colocalized with the Xist RNA-coated chromatin of the inactive X chromosome (Xi) in ovarian cancer cells." (PMID 29921308, 2018). "The majority of patients (86%) had a primary diagnosis of ovarian cancer, and 45% (42/93 patients) had known germline BRCA1/2 mutations." (PMID 29313279, 2018). "The association of BRCA1/2 mutations with improved OS and progression-free survival has been previously reported in ovarian cancers." (PMID 30382883, 2018). "There are five major histologic subtypes of ovarian cancer and high grade serous cancer (the most common) is reported in 75–100% of BRCA1 and BRCA2 mutation carriers." (PMID 29506471, 2018). "In a mouse model that has been inoculated with the BR5FVB1-Akt cell line, a BRCA1-deficient ovarian cancer, PARPis induce a local immune response." (PMID 30487462, 2018). "In familial breast or ovarian cancer, women can access early screening, chemoprevention, or risk reducing surgery only if they know they have inherited the BRCA1/2 mutation." (PMID 29622529, 2018). "Echoing modern medical development, BRCA1/2 mutations have been correlated with high efficiency of poly(adenosine diphosphate-ribose) polymerase inhibitors in ovarian cancer." (PMID 29729664, 2018). "In fact, PARP inhibitors (iPARP) have recently been approved for the treatment of advanced ovarian cancer patients carrying either germline or somatic mutations in BRCA1/2 genes." (PMID 30103829, 2018). "Germline BRCA1 pathogenic variants predispose to an increased lifetime risk of breast and ovarian cancer." (PMID 30283497, 2018). "A recent study carried out on many ovarian cancer patients showed that 3.6% displayed germline BRCA1 mutations, 3.3% germline BRCA2 mutations and 2.9% germline RAD15C mutations." (PMID 29389895, 2018). "Considering all (40 = 16+24) patients with ovarian cancer, applying a two-step algorithm enabled detection of 40% (16/40) more patients with BRCA1/2 mutations potentially benefiting from PARP inhibitor therapy." (PMID 30040829, 2018). "BRCA1 is a well-characterized breast and ovarian tumor suppressor, females with mutations in BRCA1 are predisposed to develop breast and ovarian cancers." (PMID 29921308, 2018).
ovarian carcinoma (continued). "The cumulative risk for developing ovarian cancer is estimated to be 39% and 11% for BRCA1 and BRCA2 mutation carriers, respectively." (PMID 30174725, 2018). "The estimated penetrance of ovarian cancer by age 70 years was 21.5% (95% CI: 10.4-37.0%) for BRCA1 mutation carriers and 7.3% for BRCA2 mutation carriers." (PMID 29861850, 2018). "This review summarizes the available data on the impact of variants on non-coding regions of BRCA1/2 genes and their role on breast and ovarian cancer predisposition." (PMID 30453575, 2018). "The importance of BRCA1/2 mutation screening in ovarian cancer patients has been further underscored by recent findings showing that mutation carriers have increased sensitivity to inhibitors of poly (ADP-ribose) polymerase (PARP)." (PMID 30103829, 2018). "In these BRCA carriers, the lifetime risk of ovarian cancer ranges from 40–60% for BRCA1 and 10–30% for BRCA2, respectively." (PMID 30424539, 2018). "It showed impactful response rates in the BRCA1 or BRCA2-mutated platinum-sensitive ovarian cancer patients." (PMID 30050740, 2018). "Among the 10 women with ovarian cancer and a BRCA1 mutation, six reported a first- or second-degree relative with breast or ovarian cancer (60%)." (PMID 29492181, 2018). "It is well established that germline BRCA1 mutations are responsible for many familial cancer types including breast and ovarian cancers." (PMID 30049288, 2018). "Decreased BRCA1 expression is associated with tumorigenesis of ovarian cancer, but is also associated with platinum sensitivity and better prognosis." (PMID 29712898, 2018). "Genetic testing for BRCA1/2 mutation carriers proves critical to clinical decisions, as more than 90% of the cases of epithelial ovarian cancer (EOC) are diagnosed with bulky intra-abdominal disease or distant metastases." (PMID 30103829, 2018). "In preclinical combination studies, CTLA-4 blockade has been shown to synergise with PARP inhibition in Brca1-deficient mouse models of ovarian cancer in a manner dependent on IFN-γ secretion into the TME." (PMID 29123260, 2018). "The estimates of ovarian cancer penetrance by age 70 were 39% (95% CI: 34-45%) for BRCA1 mutation carriers and 17% (95% CI: 13- 21%) for BRCA2 mutation carriers." (PMID 29861850, 2018). "Missense mutation at the Cys61 (C61G) of BRCA1 is a founder mutation in Polish population and is included as a standard test for diagnosis and treatment of breast and ovarian cancer for Polish women." (PMID 29459887, 2018). "PARP inhibitors are small molecule inhibitors that have recently been approved for platinum-sensitive relapsed and platinum-resistant ovarian cancers specifically harboring BRCA1 or BRCA2 mutations." (PMID 30551670, 2018). "This latter effect is the opposite of what one would expect from a BRCA1/2 variant associated with an increased breast/ovarian cancer risk." (PMID 30453575, 2018). "Salpingo-oophorectomy—surgical removal of the ovaries and fallopian tubes—is the standard preventive surgery recommended for germline BRCA1/2 carriers, who are at high risk of ovarian cancer." (PMID 30424539, 2018). "BRCA1 mutation carriers tend to develop ovarian cancer at a younger age compared to BRCA2 mutation carriers." (PMID 30174725, 2018). "Silencing of the BRCA1 gene by promoter hyper-methylation has also been detected in primary breast and ovarian carcinomas, especially during loss of heterozygosity and in specific histopathologic subgroups." (PMID 30613364, 2018). "Our article uses the largest familial study of ovarian cancer to argue that there exists an ovarian cancer susceptibility gene on the X-chromosome acting independently of BRCA1 and BRCA2." (PMID 29447163, 2018). "Since their discovery, hundreds of mutations have been discovered in the BRCA genes that predispose the individual to an increased risk of breast and ovarian cancer, such as BRCA1.185delAG, BRCA1.5382insC and BRCA2.6174delT in Ashkenazi Jews." (PMID 30174725, 2018).
ovarian carcinoma (continued). "Women with BRCA1/2 germline mutations have a high lifetime risk for developing both BC and ovarian cancer (OC) compared to women from the general population." (PMID 29884136, 2018). "This reflects an awareness, amongst BWA v3 users, of studies that describe the performance of the model in predicting the likelihood of carrying a BRCA1 or BRCA2 mutation or the risk of developing breast or ovarian cancer in different populations." (PMID 28623477, 2018). "In ovarian cancer, the hereditary factor, represented by mutations in BRCA1 or BRCA2, is a strong prognostic factor." (PMID 29445866, 2018). "Several successful clinical trials have resulted in PARPi being approved for the treatment of advanced stage BRCA1/BRCA2-deficient ovarian cancer patients that have been pre-treated with chemotherapy, or who have undergone surgery." (PMID 30680069, 2018). "Forty out of 60 BRCA1 mutations were beyond the ovarian cancer cluster region (OCCR), in stark contrast with 22 out of 36 BRCA2 mutations being inside the OCCR." (PMID 30103829, 2018). "Although germline mutations of BRCA1 are a risk factor of hereditary breast and ovarian cancers among women, their occurrence is less frequent in sporadic cancers." (PMID 30176860, 2018). "It should be noted that the eMERGE project is only returning results from two genes that are associated with breast and/or ovarian cancer risk (BRCA1 and BRCA2)." (PMID 30011878, 2018). "Regarding the spectrum of mutations along the genes, 40 out of 60 mutations detected in BRCA1 were located outside the ovarian cancer cluster region (OCCR), in contrast with the findings for BRCA2, in which 22 out of 36 were located inside the OCCR." (PMID 30103829, 2018). "A Colombian study has reported 100 patients with ovarian cancer diagnosis and 15% of mutation detection—13% in BRCA1 and 2% in BRCA2—including an 11% accounting for a founder mutation." (PMID 30103829, 2018). "In the most recent prospective report, the cumulative risk of epithelial ovarian cancer to age 80 was 49% for BRCA1 and 21% for BRCA2 mutation carriers." (PMID 30572612, 2018). "In a cohort of 26 platinum-resistant ovarian cancer patients carrying BRCA1/2 mutations, 46.2% had secondary mutations." (PMID 30347758, 2018). "The aim of our study is to estimate breast and ovarian cancer risk in Chinese female BRCA1/2 mutation carriers using a more efficient method based on a relatively large study population." (PMID 29861850, 2018). "It has been shown that ovarian cancer patients from Poland are characterized by a high proportion of a limited number of recurrent mutations in BRCA1." (PMID 29492181, 2018). "Approximately 6% of unselected ovarian cancer patients in the region of Podkarpacie Poland carry a BRCA1 causative founder variants." (PMID 29492181, 2018). "Epigenetic silencing of RAD51C has been described in ovarian cancer with BRCA1 deficiency but not in TGCTs." (PMID 29898407, 2018). "BRCA1 is frequently mutated in inherited breast and ovarian cancers though somatic mutations rarely reported in sporadic cases." (PMID 29932172, 2018). "A BRCA1 causative founder variants were detected in 10 of the 158 (6.3%) unselected ovarian cancer cases." (PMID 29492181, 2018). "BRCA1 was mutated in 19% of our patients, which, intriguingly, occurred exclusively in drug‐resistant recurrent ovarian cancer patients." (PMID 29797793, 2018).
ovarian carcinoma (continued). "This renders the constitutive BRCA1 promoter methylation as a potential predictive biomarker for breast and ovarian cancer predisposition." (PMID 30049288, 2018). "Germline mutations in BRCA1 are associated with increased risk of breast and ovarian cancer and BRCA1 deficient tumors are exquisitely sensitive to poly (ADP-ribose) polymerase (PARP) inhibitors." (PMID 29511213, 2018). "The poly-ADP-ribose polymerase (PARP) inhibitor olaparib, a targeted therapeutic drug approved by the Food and Drug Administration, is used to treat ovarian cancer patients with BRCA1 and BRCA2 mutations." (PMID 30453999, 2018). "Somatic BRCA1/2 pathogenic variants are reported to be present in about 7% of ovarian cancers in the first line or platinum-sensitive relapsing patients." (PMID 29731958, 2018). "The study of the whole spectrum of mutations in BRCA1/2 enables genetic counseling to be optimally implemented and enables the largest group of women at a high risk of developing BRCA1/2-related breast or ovarian cancer to be identified." (PMID 30040829, 2018). "Cumulative lifetime risk of ovarian cancer associated with a BRCA1 or BRCA2 mutation is estimated at 44% and 17%, respectively, with 15.5% of patients with epithelial ovarian cancer found to carry a mutation." (PMID 29752676, 2018). "Elevated PARP1 expression has been detected in several tumor types including breast and ovarian cancer with a further rise in triple-negative breast cancer and BRCA1- or BRCA2-mutated cancers." (PMID 29228718, 2017). "Recently, olaparib, an agent that targets several PARP isoforms including PARP1, PARP2 and PARP3, has been approved for the treatment of ovarian cancer in patients harboring deleterious mutations of the BRCA1/2 genes." (PMID 28108739, 2017). "A total of 108 patients with germline BRCA1/2 mutation advanced ovarian cancer from eight cancer centers who had been treated with olaparib at a dose of 200mg BID or greater were included in our study." (PMID 28454085, 2017). "The population-based ovarian cancer PRS was strongly associated with ovarian cancer risk in BRCA1 carriers with a per SD HR of 1.28 (95% CI = 1.22 to 1.34, P = 2.5×10−26)." (PMID 28376175, 2017). "This is the first evaluation of the combined effects of all known common breast and ovarian cancer susceptibility loci on cancer risks for women who carry a BRCA1 or BRCA2 mutation." (PMID 28376175, 2017). "With the recent introduction of Poly(ADP‐ribose) polymerase inhibitors, a promising novel therapy has become available for ovarian carcinoma (OC) patients with inactivating BRCA1 or BRCA2 mutations in their tumor." (PMID 27767231, 2017). "The risk of developing breast and ovarian cancer is higher in families that carry mutations in BRCA1 or BRCA2 genes, and timely mutation detection is critical." (PMID 29021639, 2017). "No conclusive evidence of association between AR CAG repeat size and ovarian cancer risk in Jewish BRCA1/2 mutation carriers." (PMID 27741511, 2017). "Although the majority of BC and OC cases are sporadic, approximately 10% of ovarian cancer cases and 3–5% of BC cases are due to germline mutations in the genes BRCA1 and BRCA2, which has been described as hereditary breast-ovarian cancer (HBOC) syndrome." (PMID 28961279, 2017). "Among them are phase 2 trials with the next‐generation CHK‐1 inhibitor prexasertib as a single agent in BRCA1/2 mutation‐associated breast or ovarian cancer and in patients with solid tumors with replicative stress or homologous repair deficiency." (PMID 28766886, 2017). "Here, for the first time we established the frequency of the germline and somatic BRCA1/2 mutations in 121 ctDNA samples from unselected ovarian cancer patients by using the comprehensive mutational analysis with NGS." (PMID 29254167, 2017). "This is reminiscent of the frequency of parallel evolution of resistance to PARP inhibitors in ovarian cancers through BRCA1/2 reversion mutations." (PMID 28810143, 2017).